IL6 (interleukin 6)
Diseases named in the same sentence as IL6 in open-access papers (continued):
Sharing a sentence is not in itself a finding about the gene and the disease.
tumor (continued). "TLR-4 and IL6 expression in the tumor microenvironment were associated with adenocarcinoma in human samples and in the murine model." (PMID 21059221, 2010). "Immunohistochemistry revealed that loss of tumour expression of sIL-6R was significantly inversely correlated with intense IL-6 expression in the cytoplasm of cancer cells." (PMID 20823887, 2010). "To test the input of identified cytokines in stimulation of invasion we chose IL-6 because of its well known association to tumour progression." (PMID 20723242, 2010). "Aberrant production and signaling of circulating IL-6 has been implicated in tumor generation and poor disease outcome in various cancers." (PMID 20374625, 2010). "IL-6 induction and expression in tumor cells and tumor associated myeloid cells has an important role in chronic inflammatory oncogenic signaling, likely by activation of the STAT-3 transcriptional activator." (PMID 21429243, 2010). "In neoplasia, several factors including IL-1, IL-6, PTHrP, RANKL and MIP-1alpha, have been implicated in osteoclast formation and bone destruction." (PMID 20976205, 2010). "Significantly, bronchoalveolar adenocarcinomas in STAT3C transgenic mice were preceded by inflammatory cell infiltrates and tumour development was associated with excessive secretion of inflammatory cytokines, including IL6." (PMID 20478049, 2010). "More recently, IL-6 overexpression in the serum and in tumour specimens of pancreatic cancer patients has been linked with accelerated weight loss." (PMID 19127266, 2009). "A number of antibodies have been developed to target pro-inflammatory cytokines, including TNF-α, IL-6 and IL-6 receptor, and these should be investigated for their potential to reverse tumour-associated impairment of drug metabolism." (PMID 19450285, 2009). "Circulating concentrations of IL-1β, IL-6 and TNFα and other cytokines have been associated with anorexia and weight loss in rodent tumour models and in human participants." (PMID 19127266, 2009). "Many tumor-derived factors, such as interleukin-6, prostaglandins and VEGF, are implicated in both processes." (PMID 19519895, 2009). "IL-6 has further been implicated in promotion of tumour growth, invasion and metastasis, and the development of drug resistance." (PMID 18059400, 2008). "This was associated with increasing levels of both circulating IL-6 (P<0.05; 95% CI: 1.2–2.9) and mRNA expression levels of IL-6 within the tumour itself (P<0.05; 95% CI: 1.0–2.6)." (PMID 18059400, 2008). "In NSCLC patients elevated IL-6 plasma levels were related to tumour size, increased with tumour progression and have been associated with a worse prognosis." (PMID 18682839, 2008). "In summary, an elevated preoperative C-reactive protein was associated with increased tumour stage, interleukin-6 and interleukin-10 concentrations." (PMID 17003778, 2006). "An elevated preoperative C-reactive protein was associated with increased tumour stage, interleukin-6 and interleukin-10 concentrations." (PMID 17003778, 2006). "Elevated serum levels of IL-6 have been associated with increased tumour burden and more advanced disease in several cancer types including colorectal, ovarian and breast." (PMID 14735187, 2004). "Apart from the current study, however, there has been only one report of an association between the IL-6 −174 G/C polymorphism and tumour phenotype." (PMID 14735187, 2004). "IL-2 is also released by tumour infiltrating lymphocytes (TILs) and IL-6 is released by tumour associated macrophages (TAMs), TILs and fibroblasts." (PMID 15272933, 2004). "Further prospective studies will be required to elucidate the relationships between the −174 G/C polymorphism, serum IL-6 levels, normal and tumour tissue IL-6 levels, and the biological phenotype for different cancers." (PMID 14735187, 2004).
tumor (continued). "It has also been demonstrated that elevated IL-6 levels are associated with a poor prognosis in tumours such as non-small-cell lung cancer." (PMID 15150588, 2004). "At least two other studies have reported an association between low tissue expression of IL-6 and aggressive tumour behaviour." (PMID 14735187, 2004). "Moreover, cellular components such as cancer-associated fibroblasts (CAFs), tumor-associated macrophages (TAMs), and regulatory T cells (Tregs) drive immune evasion and therapeutic resistance via cytokine signaling axes, including IL-6/STAT3 and CXCL12/CXCR4." (PMID 42294061, 2026). "In HCC, low expression of circPTPN12 is associated with poor prognosis and promotes tumor progression by activating the NF-κB pathway, which in turn enhances the secretion of immunosuppressive cytokines such as IL-6 and TNF-α, fostering an immune-resistant microenvironment." (PMID 41602547, 2026). "A recent review suggested recruitment of ASCs from ppWAT into PCa cells and the TME are precursors to tumor stromal cells and cancer‐associated fibroblasts and a source of IL‐6, TNFα, CXCL1, CXCL5, CXCL8, CXCL12, MCP‐1, and leptin facilitating tumor angiogenesis and cancer cell proliferation." (PMID 41450167, 2026). "Besides TGF-β, one of the primary candidates is IL-6, which has been found to be elevated in both serum and tumour sites in HNSCC patients and is associated with higher staging and poor prognosis." (PMID 39858048, 2025). "Also, tumor-associated macrophages promote the progression of precancerous lesions by the secretion of interleukin-6 (IL-6)." (PMID 40427222, 2025). "PKCζ deficiency instead leads to IL‐6 overexpression and accelerates tumor growth." (PMID 41244006, 2025). "In addition to intrinsic STAT3 activation, tumor-associated macrophages (TAMs) exacerbate muscle degeneration by secreting pro-inflammatory cytokines, particularly IL-1α and IL-6, which activate STAT3 signaling in muscle fibers." (PMID 40704145, 2025). "This discrepancy may suggest a more prominent role for IL-6 in tumor-associated inflammation than TNF-α." (PMID 41155372, 2025). "In addition, most patients with a favorable tumor histology presented low levels of IL-6 (44.4%) and TNF-α (55.6%); however, these associations were not significant p = 0.05 and p = 0.07 respectively (Table A2)." (PMID 40722593, 2025). "Taken together, RETA led to remarkable reductions in tumor progression that persisted even when the intervention was withdrawn and weight rebounded along with elevated adipokines and cytokines associated with cancer, namely leptin and IL-6." (PMID 40094000, 2025). "Furthermore, tumor cells activated by the PI3K/AKT pathway secrete IL-6 and TGF-β, recruiting cancer-associated fibroblasts (CAFs) and stimulating their collagen secretion, thereby forming a pro-fibrotic extracellular matrix." (PMID 40438678, 2025). "ESCC tumor cells and surrounding stromal cells (e.g., tumor-associated macrophages, TAMs) can continuously secrete large amounts of pro-inflammatory cytokines (e.g., IL-6, IL-8, TNF-α) and growth factors (e.g., VEGF)." (PMID 41141695, 2025). "Furthermore, deficiency of circRNA-14,052 reduced xenograft tumor growth in vivo through targeting miR-214-3p/IKBKB/IL-6/JAK2/STAT3 axis." (PMID 41044672, 2025). "Notably, the IRE1α-XBP1 signaling pathway has also been linked to tumor progression and therapy resistance, in part through the positive regulation of IL-6 in several types of cancer, including hepatocellular carcinoma and melanoma." (PMID 40278350, 2025). "Cytokines such as IL-1β and IL-6, secreted predominantly by tumor-associated macrophages and stromal cells, in concert with suboptimal concentrations of TME-derived TGF-β, drives Treg-to-Th17 reprogramming through Foxp3 suppression and impairment of regulatory function." (PMID 41181112, 2025).
tumor (continued). "Elevated cytokines (IL-22, IL-6) in plasma and tumor tissue are associated with resistance to EGFR-TKI therapy.Targeting cytokines (IL-6, IL-8, TGF-β) combined with EGFR-TKIs may help overcome resistance in NSCLC." (PMID 40002883, 2025). "Moreover, dysregulated expression of TNF-α, IL-6, and IL-1β was closely associated with altered cellular microenvironments and tumor pathological progression." (PMID 41323840, 2025). "In case of IL‐6, cancer‐associated fibroblasts, tumor infiltrating lymphocytes, and/or tumor‐associated macrophages in the tumor microenvironment explain higher levels of IL‐6 in saliva and its drop after tumor removal." (PMID 40831233, 2025). "In addition, subgroup analyses were planned to assess the association between IL-6 levels and irAEs depending on clinically relevant variables —including age, sex, tumor origin and comorbidities— in a pan-cancer cohort of ICI-treated patients." (PMID 41019062, 2025). "In ovarian cancer, elevated IL-6 levels have been linked to tumor progression and poor prognosis." (PMID 40563999, 2025). "For example, 1G12 and ET58 recognize distinct epitopes, and stronger or more accessible epitope engagement by 1G12 may increase cell-surface crosslinking, amplifying downstream pro-inflammatory signaling (e.g., IL-6) in tumor-associated or myeloid cells." (PMID 41154412, 2025). "Tumor markers, such as LDH, established a positive correlation with IL-6 and S100 proteins, suggesting that their high levels could indicate a risk of tumor cell resistance to therapy." (PMID 40564098, 2025). "Specifically, tumor-associated macrophages (TAMs) create an immunosuppressive milieu through the production of a plethora of paracrine factors (IL-6, IL-12, TNF-alpha, TGF-beta, CCL1, CCL18) promoting the acquisition by CSCs of a stem-like, invasive and metastatic phenotype." (PMID 39981232, 2025). "Furthermore, cytokines and signaling molecules such as IL-33, IL-6, GM-CSF, IL-4, and IL-10 orchestrate histone modification patterns in tumor-infiltrating MDSCs and tumor-associated macrophages (TAMs), enhancing their immunosuppressive functions." (PMID 41301911, 2025). "However, elevated levels of tumor-promoting cytokines, including TNFα and IL6, were associated with poorer PFS, emphasizing the need for precise modulation of immune responses to optimize clinical outcomes." (PMID 40433369, 2025). "Elevated circulating IL-6 levels are associated with survival in LC44 through tumor progression." (PMID 41179937, 2025). "Moreover, IRE1α has been linked to the regulation of key cytokines such as IL-6 and IL-8—both central to immune recruitment, angiogenesis, and tumor-associated inflammation." (PMID 41350724, 2025). "Moreover, the expression of genes associated with apoptosis (Bax and Bcl2) and inflammation (Il6 and IL1b) in tumor tissues was notably modulated by rapamycin." (PMID 40361560, 2025). "More-aggressive tumour behaviour and treatment resistance have been linked to elevated IL-6 levels." (PMID 40724564, 2025). "Therefore, chromosomally unstable tumors have anti-tumor properties, including activation of cytotoxic type I IFN signaling and anti-tumor immunity; however, they also have tumor-promoting properties, associated with NF-κB and IL-6 signaling." (PMID 40136696, 2025). "Within the tumor stroma, metformin can dampen pro-inflammatory cytokine production; for example, in vitro studies show inhibition of NF-κB in cancer-associated fibroblasts, reducing IL-6 secretion." (PMID 41374963, 2025). "Elevated IL-6 concentrations are linked to tumor growth stimulation." (PMID 40143164, 2025). "Considering that IL-6 can trigger the same effects as FbCM, and given that the IL-6/IL-6R pathway is highly activated in HNSCC tumour, we next investigated whether Fb secreted IL-6 is causing the FbCM-induced EMT and increased radioresistance in HNSCC." (PMID 39858048, 2025).
tumor (continued). "Elevated CLR integrates two critical biological processes: C-reactive protein (CRP) elevation reflects IL-6-driven hepatic synthesis in response to tumor-associated inflammation, while lymphocytopenia indicates immunosuppression and reduced cytotoxic T-cell activity." (PMID 41451214, 2025). "Furthermore, tumor‐associated stromal cells engage tumor and tumor‐supportive cells to promote cancer progression by secreting protumorigenic cytokines such as IL‐6 and IL‐8." (PMID 41049266, 2025). "In solid tumors with elevated proliferating cell nuclear antigen (PCNA) levels and reduced phosphatase and tensin homolog deleted on chromosome ten (PTEN), androgen receptor, caspase-3, and Bcl-2-associated X protein (Bax) levels, high IL-6 amounts contribute to tumor development." (PMID 40420174, 2025). "Elevated circulating monocytes serve as precursors of tumor-associated macrophages (TAMs), which accumulate within the tumor microenvironment and are sustained by inflammatory mediators such as IL-6, tumor necrosis factor-α (TNF-α), and prostaglandin E2 (PGE2)." (PMID 41487591, 2025). "Some patients may also experience constitutional symptoms (e.g., fever, fatigue, weight loss), attributed to elevated interleukin-6 (IL-6) levels produced by tumor cells." (PMID 40630762, 2025). "This analysis showed that low levels of IL-6 were significantly associated with a lower risk of presenting an unfavorable tumor histology (p = 0.048; OR = 0.17, 95% CI = 0.032–0.98) and that high levels were associated with a higher risk of death (p = 0.022; OR = 15.99, 95% CI = 1.49–171.2)." (PMID 40722593, 2025). "For instance, cancer-associated fibroblasts exhibit various cellular subtypes; among them, CD10+GPR77+ cancer-associated fibroblasts continuously secrete IL-6 and IL-8 to maintain the differentiation potential of tumor stem cells, thereby inducing the onset of drug resistance." (PMID 39996893, 2025). "The antitumor response was linked to the accumulation of M1-type macrophages in the tumor microenvironment and the overexpression of mRNA for antitumor mediators Inducible Nitric Oxide Synthase, Tumor Necrosis Factor-alpha, and Interleukin-6 (iNOS, TNF-α, and IL-6)." (PMID 40931613, 2025). "Notably, IL-6 and IL-10 have been shown to prominently induce T cell dysfunction, with IL-6 particularly implicated in poor tumor prognosis." (PMID 41200178, 2025). "This elevation in IL‐6 is associated with a decrease in activated NK cells within the tumor." (PMID 40859900, 2025). "Similarly, in GC cells, tumor-associated macrophages can promote GC cell proliferation by inducing PD-L1 expression through IL-6 and TNF-ɑ signaling." (PMID 41444219, 2025). "In addition, Overexpression of PPARβ/δ also increases the incidence rate of colitis-associated colorectal cancer by mediating IL-6/activator of transcription 3 (STAT3) signaling to promote the expression of tumor-promoting genes, such as Notch3 and MUC1." (PMID 39875357, 2025). "Furthermore, we identified a significant increase in interleukins and tumour necrosis factors, including IL‐1a, IL‐1b, IL‐6, IL‐17C, IL‐32, IL‐36G and TNF, along with its associated enzyme." (PMID 39865778, 2025). "Skewing of the DC phenotype is driven by a complex interplay of factors, with key drivers being anti-inflammatory cytokines, predominantly secreted by tumor cells and cancer-associated fibroblasts, such as IL-6, IL-10, vascular endothelial growth factor (VEGF) and transforming growth factor (TGF)-β." (PMID 41086813, 2025). "Thus, CV increases the production of TNF-α, IL-6, and other proinflammatory cytokines, promoting M1 polarization of tumor-associated macrophages (TAMs) and reducing angiogenic factors such as VEGF and MCP-1." (PMID 41150756, 2025). "Furthermore, CAFs promote tumor growth and metastasis via secretion of IL-6, causing the endothelial–mesenchymal transition, a key feature of metastatic cancer cells." (PMID 40227764, 2025).
tumor (continued). "Additionally, the thrombopoietic cytokine interleukin-6, produced by tumour tissues, has been linked to platelet levels." (PMID 40332145, 2025). "The expression of IL-6 also increases angiogenesis, an important hallmark of cancer; it is this formation of new blood vessels which provides the nutrients necessary for further tumor growth." (PMID 40725140, 2025). "Furthermore, elevated IL-6 in PCa serum and tumor tissue is associated with disease progression and poor prognosis." (PMID 41374981, 2025). "The main cellular source of IL-6 are monocytes, T cells, epithelial cells, tumor cells and tumor-associated fibroblasts, which participate in regulating acute phase reactions, activating T helper (Th) cells, inhibiting T regulatory (Tregs) cells, and differentiating B cells." (PMID 39891057, 2025). "Of particular interest is the enrichment of M0 and M2 macrophages, which resonates with a seminal study demonstrating that radiotherapy induces a distinct, PD‐L1+ tumor‐associated myeloid subset that co‐upregulates protumorigenic factors (IL‐6, CXCL8) and immune checkpoints." (PMID 41473739, 2025). "NF-κB-induced IL6 is implicated in tumor development and growth, primarily by increasing the survival and growth of cancer cells, as well as influencing the immune system to sustain tumor-associated inflammation." (PMID 40841364, 2025). "Additionally, CD40-positive EVs were prominent, potentially linked to anti-tumor immune responses under IL-6 signaling." (PMID 40106404, 2025). "M2d macrophages, also referred to as tumor-associated macrophages, are driven by Toll-like receptor ligands, IL-6, and adenosine receptor activation, and contribute to angiogenesis and tumor progression by releasing TGF-β, IL-10, and vascular endothelial growth factor (VEGF)." (PMID 40722994, 2025). "In addition to genetic alterations, PDAC features a dysregulated immune environment with tumorigenic regulatory T cells, intratumoral macrophages producing interleukin 6 (IL-6), and cancer-associated fibroblasts (CAFs) that promote tumor progression." (PMID 40918466, 2025). "For example, cetuximab induces ICD by directly triggering ER stress on the cell surface to promote DC phagocytosis; it also indirectly induces the polarization of tumor-associated macrophages (TAMs) by inhibiting IL-6 expression via the NF-κB and STAT3 pathways." (PMID 41314288, 2025). "For instance, bortezomib, a drug that interferes with protein breakdown, can suppress tumor survival signals, while cytokine blockers such as canakinumab (which targets IL-1β) and tocilizumab (which targets IL-6) have shown the potential to lower cancer risk and improve response to therapy." (PMID 41514860, 2025). "Furthermore, pro-inflammatory diets are implicated in indirectly boosting the production of tumor-promoting cytokines like IL-6 and TNF." (PMID 38992637, 2024). "The association between IL‐6 and tumor immunology has been extensively studied in recent years." (PMID 37452653, 2024). "Moreover, this IL-6-dependent increase of VEGF expression in tumor cells is linked with the higher HIF-1α in LECs." (PMID 38361941, 2024). "Similarly, the senescent TME, enriched in adenosine due to senescent tumor cells stimulating CD73 expression on tumor-associated macrophages via IL-6 and the JAK/STAT3 pathway, impedes anti-tumor immunity." (PMID 39461979, 2024). "High TAMs is associated with invasion, migration, and IL6 for tumor progression of CRC metastasis." (PMID 38504096, 2024). "The pro-inflammatory nature of IL-6, which has been implicated in various tumor-promoting processes, suggests that its elevated levels could contribute to systemic inflammation and, in turn, reduced efficacy of immunotherapeutic interventions." (PMID 39766045, 2024). "Moreover, inhibiting their signaling with anti-IL-6R and CSF1Ri kept CD14+ cDC2 frequencies equal to tumor-free conditions, underlining IL-6 and M-CSF as dominant drivers of tumor-induced CD14+ cDC2s." (PMID 38242119, 2024).